FABP7 (fatty acid binding protein 7)
Diseases named in the same sentence as FABP7 in open-access papers (continued):
Sharing a sentence is not in itself a finding about the gene and the disease.
schizophrenia (21 papers, 2009 to 2025). A major psychotic disorder characterized by abnormalities in the perception or expression of reality. "Simultaneous allelic association studies have also revealed that the expression of FABP7 is associated with schizophrenia and bipolar disorder." (PMID 36077044, 2022). "A correlation between an SNP variant within the second exon of human FABP7 and schizophrenia pathology was observed." (PMID 34208549, 2021). "Current intriguing questions would focus on how upregulation of FABP5 and FABP7 in schizophrenia derived postmortem brains and upregulation of FABP7 in autism derived postmortem brains are associated with disease." (PMID 25027319, 2014). "A quantitative trait loci analysis for low pre-pulse inhibition (PPI), a phenotypic marker of schizophrenia, revealed a strong association with the FABP7 locus in mice, and FABP7 is significantly upregulated in human postmortem brains of schizophrenics compared to controls." (PMID 37404868, 2023). "Second, we detected a genetic association of FABP7 with both schizophrenia and bipolar disorder." (PMID 25027319, 2014). "In addition, it has been reported that increased tissue expression of fatty acid binding protein (FABP) is closely associated with the etiology of schizophrenia, and both LA and AA are bound by FABP7." (PMID 25004141, 2014). "Furthermore, we identified and reported several rare non-synonymous polymorphisms of the brain-expressed genes FABP3, FABP5 and FABP7 from schizophrenia and autism spectrum disorder (ASD), diseases known to part share genetic architecture." (PMID 25027319, 2014). "Several lines of evidence associate Fabp7 with neuropsychiatric diseases such as schizophrenia." (PMID 22701680, 2012). "Fabp7 knock-out (KO) mice have previously been shown to have altered behavioral responses, including an increase in anxiety-like behavior, and deficits in prepulse inhibition, a hallmark of schizophrenia." (PMID 21298037, 2011). "While our hypothesis is centered around AD, we hope that the pathways described here will help to elucidate those underlying other FABP7-linked conditions including cancer, Down’s syndrome, schizophrenia, amyotrophic lateral sclerosis (ALS), and Parkinson’s disease." (PMID 35844236, 2022). "Alterations in the expression of the lipid chaperone fatty acid binding protein 7 (FABP7), which is expressed primarily in astrocytes in the brain, have been found in the brains of schizophrenia patients." (PMID 38199991, 2024). "It has also been found that compared with healthy controls, levels of FABP7 mRNA are higher in the postmortem brains of patients with autism spectrum disorder and schizophrenia." (PMID 36077044, 2022). "Human FABP7 mRNA levels were significantly upregulated in the postmortem brains of schizophrenia patients." (PMID 34208549, 2021). "Evidence has shown exclusively in schizophrenia that two genetic variations of FABP7 (FABP7 S86G and FABP7 V126L) change preference from DHA to LA." (PMID 32620164, 2020). "When autism postmortem brains were analyzed, FABP7 mRNA was elevated in the frontal cortex, as in schizophrenia, and also in the parietal cortex." (PMID 25027319, 2014). "In another study, resequencing analysis of FABP3, FABP5 and FABP7 from an ASD cohort identified several rare non-synonymous polymorphisms, some of which were also seen in schizophrenia." (PMID 25027319, 2014). "It would also be interesting to elucidate how disruption of Fabp7 induces schizophrenia- and ASD-like, as well as emotion-related phenotypes in mice." (PMID 25027319, 2014). "We previously reported an association between the gene for fatty acid binding protein 7 (FABP7) and schizophrenia." (PMID 25027319, 2014). "In postmortem brains, we detected altered mRNA expression levels of FABP5 in schizophrenia, and of FABP7 in ASD and altered FABP5 in peripheral lymphocytes." (PMID 25027319, 2014).
schizophrenia (continued). "Examining ligand binding properties, FABP7 S86G and FABP7 V126L, which were detected exclusively in schizophrenia subjects and an ASD subject, respectively, lost preference for DHA to LA." (PMID 25027319, 2014). "Fabp7 maps to a quantitative trait locus for a schizophrenia endophenotype and therefore we employed a prepulse inhibition (PPI) test, which is used as a measure for schizophrenia." (PMID 24932636, 2014). "In our recent study, we identified Fabp7, that encodes a brain-type fatty acid binding protein (also known as brain lipid binding protein; BLBP) as a gene responsible for PPI in mice and showed that human FABP7 is a susceptibility gene for schizophrenia." (PMID 19352438, 2009). "In a previous study, we identified Fabp7, a fatty acid binding protein 7 as one of the genes controlling PPI in mice and showed that this gene was associated with schizophrenia." (PMID 19352438, 2009). "The potential PPI QTL gene, Fabp7, is associated with functional links to the NMDA receptor; further analysis, using engineered mice and human pluripotent stem cells, revealed a potential role of Cdh23 in PPI and CDH23 in schizophrenia." (PMID 41153356, 2025). "Moreover, fatty acid-binding protein 7 (FABP7) is critical for astrocyte-neuron lipid homeostasis, and its deletion leads to neuropsychiatric disorders such as schizophrenia, probably because of altered dendritic spine morphology." (PMID 39728504, 2024). "However, it should be noted that the polymorphism of gene for FABP-7, which transports DHA to brain cells is found to alter the specificity from DHA to LA in some schizophrenia patients." (PMID 32620164, 2020). "Fabp7 appeared in every BPD and schizophrenia-associated gene set tested in this study." (PMID 24765068, 2014). "Lack of Fabp7 in mice leads to altered emotional behavioral responses and has been associated with a schizophrenia endophenotype." (PMID 24932636, 2014). "FABP7 may act in a disease pathway shared between schizophrenia and ASD." (PMID 25027319, 2014). "Interestingly, we found that expression of FABP5 and FABP7 correlated tightly in both schizophrenia and control subjects, although the biological implications of this observation are unknown." (PMID 25027319, 2014). "These combined data imply aberrant expression of FABP7 and FABP5 genes in the brains and/or lymphocytes of schizophrenia and ASD sufferers, suggesting a pathophysiological role for these genes." (PMID 25027319, 2014). "In this study, we performed comprehensive analyses of FABP7, FABP5 and FABP3, in the context of psychiatric illnesses, particularly schizophrenia and ASD." (PMID 25027319, 2014). "Plasma FABP7 concentrations also correlated with Positive and Negative Syndrome Scale clinical scores, particularly in severities of depression/anxiety, cognition, and positive symptoms of schizophrenia patients." (PMID 37404868, 2023).
melanoma (20 papers, 2006 to 2025). A malignant, usually aggressive tumor composed of atypical, neoplastic melanocytes. "Nuclear BRMS1 was associated with expression of fatty acid binding protein 7 (FABP7; p = 0.011), a marker of invasion in melanomas." (PMID 22356677, 2012). "In addition, increased expression of FABP7 was associated with proliferation and invasion of melanoma cells." (PMID 27779102, 2016). "Moreover, FABP7 expression is associated with tumor thickness and proliferation in melanoma biopsies." (PMID 18826602, 2008). "FABP7 expression was associated with tumor thickness in superficial spreading melanoma (P = 0.021)." (PMID 18826602, 2008). "Furthermore, FABP7 is involved in cell proliferation and invasion in vitro, and may be associated with tumor progression in melanoma." (PMID 18826602, 2008). "Melanoma: In melanoma, FABP7 knockdown reduces the proliferation and migration of SK-MEL-23 cells, cyclin D1 expression, and Wnt/β-catenin activity." (PMID 40717587, 2025). "FABP7 knockdown in melanoma cell lines decreased cell proliferation and invasiveness, and similar effects of FABP7 on Wnt/β-catenin signaling were recently reported." (PMID 37207357, 2023). "The expression of CD36, MARCO, FABP4, FABP6, and FABP7 in melanoma samples and healthy skin biopsies is visualized, according to data retrieved from the IST Online database." (PMID 32209538, 2020). "Further, high tumor-grade (G3 + G4) RCCs express significantly lower levels of FABP7 mRNA than low-grade (G1 + G2) RCCs, and FABP7 is highly expressed in primary melanomas compared with metastatic melanomas." (PMID 28292269, 2017). "We have recently demonstrated an association between protein expression of fatty acid binding protein 7 (FABP7) and proliferation and invasion of melanoma cells." (PMID 22356677, 2012). "When examining the melanoma panel for a possible association between BRMS1 and FABP7, a significant correlation between nuclear BRMS1 expression (percentage of immunoreactive cells) and the level of FABP7 (p = 0.011) was observed." (PMID 22356677, 2012). "To further clarify the role of FABP7 in melanomas we used siRNA to down-regulate its expression in the primary WM35 and metastatic WM239 melanoma cell lines." (PMID 18826602, 2008). "FABP7 mRNA and protein level is down-regulated following treatment of melanoma cell lines with a PKC activator (PMA) or MEK1 inhibitor (PD98059)." (PMID 18826602, 2008). "In clinical specimens, FABP7 was expressed in 91% of nevi, 71% of primary melanomas and 70% of metastases, with a cytoplasmic and/or nuclear localization." (PMID 18826602, 2008). "We studied the functional role of FABP7 in human melanoma cell lines and using immunohistochemistry analyzed its expression pattern and clinical role in 11 nevi, 149 primary melanomas and 68 metastases." (PMID 18826602, 2008). "The number of invading cells was reduced by 55% and 40% in WM35 and WM239 cell respectively after transfection with FABP7 siRNA compared with scrambled siRNA control-transfected cells, suggesting that FABP7 contributes to the invasiveness of melanoma cells." (PMID 18826602, 2008). "This down-regulation notably inhibited proliferation in both cell lines, but did not affect the degree of apoptosis, arguing for involvement of FABP7 in melanoma proliferation." (PMID 18826602, 2008). "In the current study we examined the role of FABP7 in proliferation, apoptosis and invasion of melanoma cells grown in vitro and studied possible regulation mechanisms of this protein." (PMID 18826602, 2008). "The higher expression of FABP7 in nevi compared to melanomas seems contradictory to the in vitro data in the present study, as well as to the association with clinical parameters of disease progression." (PMID 18826602, 2008). "Statistical analysis demonstrated a significant higher cytoplasmic FABP7 expression in nevi compared to primary and metastatic melanomas (P = 0.023), with comparable nuclear expression." (PMID 18826602, 2008).
melanoma (continued). "In order to examine the clinical relevance of FABP7, paraffin-embedded tissue from a panel of benign nevi and primary and metastatic melanomas was analyzed for expression of FABP7 protein using immunohistochemistry." (PMID 18826602, 2008). "PKC activation and MAPK/ERK1/2 down-regulation had opposite effect on anchorage-independent survival of the melanoma cells, but both negatively regulated FABP7." (PMID 18826602, 2008). "To examine if FABP7 is frequently expressed in melanoma cell lines we analyzed the level of FABP7 mRNA and protein in two primary (WM1341 and WM902B) and seven metastatic cell lines (WM239, WM45.1, WM983, WM9, LOX, MeWo and FEMX-I) in addition to WM35." (PMID 18826602, 2008). "Together this suggests that FABP7 can be regulated by both signaling pathways independently in melanoma cells." (PMID 18826602, 2008). "We confirmed that FABP7 protein is expressed in melanocytic lesions and showed that it can regulate proliferation and invasion in melanoma cells in vitro." (PMID 18826602, 2008). "Greater FABP7 expression was seen in rarely metastasized melanoma cell lines compared to their frequently metastasizing counterparts." (PMID 16623952, 2006). "We also looked up various genes classically expressed by Schwann cell precursors or Schwann cells and found that Gap43, Fabp7, Mpz, Dhh, Ngfr, Ncam1, and Mbp were all significantly upregulated in the sparse pigment tumors than in the intradermal melanomas, as was Plp1." (PMID 39804140, 2025). "Ligand-bound FABP7 can drive melanoma cell proliferation by modulating Wnt/β-catenin signaling." (PMID 40717587, 2025). "Similarly, FABP7, characteristic of glial/neural progenitors, is frequently expressed in melanoma, promoting proliferation and invasion via PKC–MAPK/ERK signaling and integrating lipid metabolism with cell state." (PMID 41465101, 2025). "FABP7 is overexpressed and promotes cell proliferation and survival in melanoma and colon cancer." (PMID 35783014, 2022). "In addition, FABP7 is highly expressed in melanoma, breast cancers, renal cancers, regulating their proliferation, and its expression level in these tumors is correlated with patient survival." (PMID 34716958, 2022). "In addition CT16 enhanced the expression of fatty acid binding protein 7, a known promoter of melanoma progression." (PMID 23028975, 2012). "Furthermore, in a recent study we showed that expression of fatty acid binding protein 7 (FABP7) is higher in benign nevi than in melanomas, still FABP7 was suggested to contribute to disease progression, most likely by increasing tumor cell invasion." (PMID 22356677, 2012). "Recently, two studies have addressed FABP7 expression in surgical specimens from melanoma patients." (PMID 18826602, 2008). "Thus, the biological role and detailed functional mechanism of the FABP7 protein in melanoma cells remains to be further investigated." (PMID 18826602, 2008). "In addition, we examined the expression of FABP7 protein in clinical melanoma specimens and assessed the relationship between FABP7 expression pattern and known prognostic variables, cell cycle factors and disease progression." (PMID 18826602, 2008). "This demonstrates a regulatory function for INHBA, FABP7, ANGPTL4, and CYR61 in melanoma cell migration." (PMID 29454361, 2018). "FABP7 was found to be up-regulated, again supporting the results obtained from SKMEL28 melanoma cells." (PMID 29454361, 2018). "Next, we investigated a possible impact of the four selected genes (INHBA, FABP7, ANGPTL4, and CYR61) on overall survival of melanoma patients." (PMID 29454361, 2018). "CT16 also enhances the expression of fatty acid binding protein 7 (FABP7), a known promoter of melanoma progression." (PMID 23028975, 2012). "Our results indicate that BRN2 represses the FABP7 promoter and suggests that regulation of FABP7 expression by BRN2 differs between RCCs and melanomas." (PMID 21771320, 2011).
melanoma (continued). "Our data suggest that FABP7 can be regulated by PKC and the MAPK/ERK1/2 pathway through independent mechanisms in melanoma cell lines." (PMID 18826602, 2008). "We report that FABP7 is regulated via PKC and the MAPK/ERK1/2 signaling pathway in melanoma cells in vitro and promotes proliferation and invasion." (PMID 18826602, 2008). "In addition, CT16 enhanced the expression of fatty acid binding protein 7 (FABP7), a known promoter of melanoma progression." (PMID 23028975, 2012). "Together these results suggest that FABP7 is most likely involved in proliferation and not apoptosis in melanoma cells." (PMID 18826602, 2008). "Since our panel of primary and metastatic melanomas has previously been analyzed for expression of cell cycle progression markers and activation status of MAPK/ERK1/2, it was of interest to examine the relationship between FABP7 expression and the levels of these factors." (PMID 18826602, 2008).
Anxiety (14 papers, 2008 to 2025). Intense feelings of nervousness, tension, or panic often arise in response to interpersonal stresses. "Following single-prolonged stress, a rodent model for post-traumatic stress disorder, we observed disrupted unconditioned anxiety in FABP7 KO mice compared to WT mice, which was also associated with abnormal stress-dependent sleep suppression." (PMID 37404868, 2023). "Fabp7 has recently been implicated in fear memory and anxiety and we therefore examined the region-specific distribution of Fabp7 mRNA in amygdala and hippocampus." (PMID 18286188, 2008). "We speculated that prenatal inflammation may increase the susceptibility of germ cells to anxiety via the influence of Fabp7 expression." (PMID 36299292, 2022). "The current findings supported the idea that FABP7 levels showed a genetic association with anxiety levels, and the alteration of Fabp7 gene expression may occur at the levels of transcription and/or translation." (PMID 36299292, 2022). "In addition to its role in development, it has been shown that a null mutation in Fabp7 results in a rodent phenotype characterized by elevated anxiety and fear memory." (PMID 23717492, 2013). "Fabp7-deficient mice displayed enhanced fear memory and anxiety in adulthood." (PMID 22701680, 2012). "For instance, FABP3 knockout mice exhibit reduced social memory and novelty-seeking behaviors, while FABP7 knockout mice exhibit hyperactivity and anxiety-related phenotypes." (PMID 40362160, 2025). "In order to test this, we examined changes in sleep and anxiety behavior in Fabp7 knock-out (KO) mice compared to C57BL/6N wild-type (WT) genetic background mice following SPS exposure." (PMID 36909794, 2022). "The correlations between performance in anxiety-related tasks and hippocampal FABP7 protein and mRNA levels in F2 offspring." (PMID 36299292, 2022). "To examine the effects of Fabp7 on unconditioned anxiety following trauma, we exposed KO and WT mice to the light–dark box test before and after SPS." (PMID 36909794, 2022). "Correlations between performance in anxiety-related tasks and hippocampal FABP7 protein and mRNA levels in F1 offspring." (PMID 36299292, 2022). "This work explored wider intergenerational influences and further questions regarding lineage effects on age-related anxiety-like behaviors and FABP7 protein and mRNA expression." (PMID 36299292, 2022). "In the current study, the effects of F0-generation LPS exposure on anxiety-like behaviors and Fabp7 gene expression in F1 and F2 offspring were age-dependent and sex-specific." (PMID 36299292, 2022). "We found that Fabp7 KO mice were hyperactive with an anxiety-related trait, based on a battery of behavioral tests." (PMID 25027319, 2014). "Together with the functional significance of the septum in fear, anxiety and memory, these findings suggest the possibility that Fabp7 plays an important role in emotional changes that occur during the postpartum period." (PMID 22701680, 2012). "Recently it has been shown that the targeted deletion of Fabp7 results in an enhancement of fear memory and anxiety in adulthood." (PMID 18286188, 2008). "FABP7-KO mice exhibit altered anxiety-like behavior and deficits in PPI." (PMID 37404868, 2023). "The intergenerational effect of increased anxiety-like behaviors in F2 offspring may be attributable to decreased Fabp7 transcription, which then leads to decreased translation." (PMID 36299292, 2022). "Here, we were interested in determining whether Fabp7 KO mice show changes in innate anxiety following SPS treatment, compared to WT controls." (PMID 36909794, 2022). "The current study investigated the effects of maternal (F0 generation) lipopolysaccharide administration (50 μg/kg, i.p.)during late gestation on anxiety-like behaviors and FABP7 expression in F1 and F2 offspring, as well as the potential sex-specificity of intergenerational effects." (PMID 36299292, 2022).